PVALB (parvalbumin)
Diseases named in the same sentence as PVALB in open-access papers (continued):
Sharing a sentence is not in itself a finding about the gene and the disease.
schizophrenia (continued). "In the thalamic reticular nucleus of transgenic mice with a redox dysregulation, the numbers of parvalbumin-positive neurons and PNNs were decreased in the rodent model for schizophrenia and bipolar disorders compared to wild-type (WT) mice." (PMID 40072050, 2025). "Environmental enrichment restored parvalbumin interneuron hypomyelination in the mPFC and rescued cognitive deficits in this schizophrenia-like rat model." (PMID 40518508, 2025). "The primary objective was to determine the extent of changes in parvalbumin, somatostatin, calbindin, and calretinin interneurons across brain regions and cortical layers in schizophrenia compared to healthy controls." (PMID 40501558, 2025). "Analyses of prefrontal cortex tissues from schizophrenia patients have reported significant reductions in the expression of genes associated with the GABAergic system, such as NPTX-2 and parvalbumin." (PMID 40563435, 2025). "Decreased expression of myelin-related genes, a reduced number of mature oligodendrocytes, and fewer myelinated parvalbumin inhibitory axons have been observed in the mPFC in a rat model of schizophrenia, accompanied by mPFC-dependent cognitive deficits." (PMID 40518508, 2025). "According to the literature, while the number of parvalbumin-expressing neurons remains constant, there is a considerable drop in parvalbumin expression among these neurons in patients with schizophrenia." (PMID 40711497, 2025). "Oxidative stress can damage parvalbumin interneurons and oligodendrocytes, contributing to the development of schizophrenia." (PMID 40612741, 2025). "This oxidative stress, likely driven by altered neurotransmitter signaling and cellular metabolism, is thought to contribute to schizophrenia-related deficits in inhibitory interneuron populations, including parvalbumin-positive cells." (PMID 40686501, 2025). "In the dorsolateral prefrontal cortex, the density of parvalbumin-positive cells remained unchanged in individuals with schizophrenia." (PMID 40072050, 2025). "Postmortem brain studies on schizophrenia demonstrated that the impairments in parvalbumin neurons are particularly significant in layer three of the prefrontal cortex, which plays a pivotal role in the formulation of gamma oscillations." (PMID 39201380, 2024). "Accumulating evidence from animal studies indicates that dysfunction of NMDA receptors expressed on parvalbumin interneurons mainly contributes to the pathophysiology of schizophrenia." (PMID 39201380, 2024). "Deficits of brain parvalbumin (PV) are a consistent finding in schizophrenia and models of psychosis." (PMID 39019913, 2024). "These compounds appear to normalise parvalbumin-positive cell counts in alternative models for schizophrenia and have recently shown promising effects on gamma oscillations in patients." (PMID 38363536, 2024). "Reduced frontal cortical parvalbumin expression in PCP-Iso mirrors a number of post-mortem findings from schizophrenia patients over the past 25 years." (PMID 38363536, 2024). "Schizophrenia represents a consolidated model of γ alterations arising from the aberrant activity of parvalbumin-positive GABAergic interneurons, whose dysfunction is associated with perineuronal net impairment and neuroinflammation." (PMID 38792599, 2024). "Among these subtypes, postmortem brain studies on patients with schizophrenia have reported several abnormalities in the parvalbumin neurons in the cerebral cortex." (PMID 39201380, 2024). "The cortical sites we found with altered functional MRI signal synchrony in patients with schizophrenia precisely include the set of cortical areas with high parvalbumin density in humans." (PMID 37848404, 2023). "A decrease in mRNA levels of parvalbumin has also been found in cortical post-mortem tissue from people with schizophrenia." (PMID 37872462, 2023).
schizophrenia (continued). "The parvalbumin interneuron defects identified in selected areas in post-mortem studies in patients with schizophrenia are also consistent with the anatomy of our findings." (PMID 37848404, 2023). "In generating these fast oscillations, an essential role is played by the inhibitory control exerted by parvalbumin+ gamma-aminobutyric acid (GABAergic) interneurons, a population of cells notably affected in schizophrenia." (PMID 37190501, 2023). "Thus, callosal projections originating from parvalbumin-expressing neurons represent a key circuit locus for understanding and correcting the deficits in behavioural flexibility and gamma synchrony that have been implicated in schizophrenia and related conditions." (PMID 37100905, 2023). "Inhibitory interneurons expressing the calcium binding protein parvalbumin are particularly affected in both schizophrenia and bipolar disorder, as they set a fine-tuned physiological inhibitory/excitatory balance." (PMID 37945756, 2023). "Deficient gamma oscillations in prefrontal cortex (PFC) of individuals with schizophrenia appear to involve impaired inhibitory drive from parvalbumin-expressing interneurons (PVIs)." (PMID 37398467, 2023). "Animal models in which rat were treated with MK-801 exhibited a reduction in the density of parvalbumin-immunoreactive GABAergic neurons in the mPFC, partially resembling some findings of schizophrenia post-mortem brains." (PMID 36983018, 2023). "The data strongly suggests that in schizophrenia only selective interneuron populations are affected, with alterations of somatostatin and parvalbumin neurons being the most convincing." (PMID 37131313, 2023). "In this study, we utilize a mouse neurodevelopmental model for schizophrenia that mimics prenatal pathogenesis and exhibits hypoexcitability of parvalbumin-positive (PV) neurons, as well as PV-preferential NMDAR dysfunction." (PMID 38086803, 2023). "Some of such reductions on GAD and parvalbumin findings were also seen in schizophrenia animal models and postmortem analysis of schizophrenic patients’ brains." (PMID 35250498, 2022). "The impaired 40-Hz gamma oscillations implicate abnormal functional interaction between parvalbumin-positive GABAergic neurons and pyramidal neurons in the prefrontal cortex of schizophrenia patients." (PMID 34997139, 2022). "Among the most perdurable observations in schizophrenia (SZ) is a functional impairment of cortical parvalbumin interneurons (PVIs)." (PMID 34686767, 2022). "GABAergic unbalance, mainly parvalbumin inhibitory activity, contributes to the sensorimotor gating deficits related to schizophrenia-like behaviors." (PMID 35250498, 2022). "Postmortem studies have repeatedly shown reduced expression of parvalbumin in schizophrenia along with increased methylation of parvalbumin in the hippocampus." (PMID 36291109, 2022). "This is indeed what we observed; methylation of sites in a sequence of the PVALB promoter region in humans was elevated in the hippocampus in schizophrenia." (PMID 34935080, 2022). "Promoter methylation of the PVALB gene has been reported in rats that underwent schizophrenia induction using a sub chronic regime of phencyclidine (PCP)." (PMID 34831111, 2021). "An increase in the PVALB gene promoter methylation was found to be increased in the hippocampus in schizophrenia patients’ post-mortem brain tissue." (PMID 34831111, 2021). "Published data suggest that GluN2A is involved in maturation and phenotypic maintenance of parvalbumin interneurons, and these interneurons suffer from a deficient glutamatergic neurotransmission via GluN2A-containing NMDA receptors in schizophrenia." (PMID 34685369, 2021). "Studies in patients and animal models of schizophrenia have found alterations in cortical parvalbumin (PV) expressing interneurons, making them good candidates to study the etiopathology of this disorder." (PMID 34630066, 2021).
schizophrenia (continued). "Although there are differences in the results among studies, a decrease in parvalbumin expression in the prefrontal cortex has been confirmed in schizophrenia and autism." (PMID 34955723, 2021). "This is particularly pertinent to parvalbumin-expressing neurons, which are known to downregulate parvalbumin expression upon oxidative stress and in schizophrenia patients." (PMID 34168541, 2021). "In schizophrenia, gene and protein expression of interneuron markers, particularly parvalbumin (PV) and somatostatin (SST), are often reduced in the cortex, cerebellum, and hippocampus." (PMID 34174930, 2021). "Analysis of postmortem human brain tissues revealed decreased expression of parvalbumin and parvalbumin mRNA in patients affected by schizophrenia or autism." (PMID 33841107, 2021). "Altered cortical excitation-inhibition (E-I) balance resulting from abnormal parvalbumin interneuron (PV IN) function is a proposed pathophysiological mechanism of schizophrenia and other major psychiatric disorders." (PMID 32029441, 2020). "In particular, α7 nAChRs have a crucial role in the dysfunction of cortical parvalbumin-positive GABAergic neurons, as seen in schizophrenia." (PMID 32854615, 2020). "One prominent mechanistic theory in schizophrenia research revolves around the role of N-methyl D-aspartate receptor (NMDAr)-dependent parvalbumin positive (PV+) interneuron activity." (PMID 32811878, 2020). "This assumption is supported by findings of a lower cortical parvalbumin level in schizophrenia patients pointing to a probable dysfunction of these cells in schizophrenia." (PMID 33101067, 2020). "Previous work in post-mortem brains from patients with schizophrenia have found lower expression of parvalbumin and GAD67 mRNAs in cases relative to age-matched controls." (PMID 32497062, 2020). "Here, we report an increase in parvalbumin in the cerebellum in schizophrenia independently of the mechanism of death." (PMID 32639965, 2020). "A decrease in parvalbumin expression is one of the most robust findings in post-mortem brains of schizophrenia patients." (PMID 33329132, 2020). "Decreased PPI and alterations of parvalbumin-positive interneurons are also endophenotypes that typically occur in schizophrenia." (PMID 32317624, 2020). "Collectively, these findings highlight that impairment of parvalbumin interneuron myelination is related to schizophrenia-relevant cognitive deficits." (PMID 32393757, 2020). "We previously showed that parvalbumin D2 mutant animals exhibit molecular, cellular, physiological, and behavioral impairments highly reminiscent of symptoms observed in schizophrenia patients and a parallel developmental onset." (PMID 32303857, 2020). "Among the neurons most affected in ASD as well as in schizophrenia are those expressing the Ca2+-binding protein parvalbumin (PV)." (PMID 33390904, 2020). "We further characterized VPP1, calmodulin and parvalbumin by immunoblot in a cohort consisting of 7 schizophrenia subjects, 7 matched control subjects and 6 matched non-schizophrenia suicide subjects (Cohort I)." (PMID 32639965, 2020). "Despite an increasing body of evidence demonstrating subcellular alterations in parvalbumin-positive (PV+) interneurons in schizophrenia, their functional consequences remain elusive." (PMID 31811155, 2019). "In view of this, we aimed to systematically review and meta-analyse the available evidence on parvalbumin neuronal density and mRNA brain measures in the pre-frontal cortex in people with schizophrenia." (PMID 31529297, 2019). "The reason for the decrease in the activity of parvalbumin neurons in schizophrenia patients in the reduced access to glutamate." (PMID 32116664, 2019). "Converging evidence suggests that abnormal function of GABAergic parvalbumin-positive interneurons leading to a loss of the balance between neuronal excitation and inhibition, and to deficits in neuronal synchronization, may contribute to cognitive deficits in schizophrenia." (PMID 29616444, 2019).
schizophrenia (continued). "Parvalbumin immunoreactive (PV-IR) cell, oligodendrocyte and myelination impairment have been reported in schizophrenia." (PMID 30800096, 2019). "After correction for potential publication bias the effect size reduction seen in parvalbumin cell density in patients with schizophrenia remained significant (Hedges’ g = − 0.29; p = 0.01)." (PMID 31529297, 2019). "Following correction for publication bias, the effect size decrease in parvalbumin mRNA in patients with schizophrenia remained unchanged (Hedges’ g = − 0.44; p = 0.12)." (PMID 31529297, 2019). "Four studies (comprising 138 schizophrenia patients and 137 healthy controls) measured parvalbumin mRNA in pre-frontal regions." (PMID 31529297, 2019). "Zhang and Reynolds (2002) reported a significant deficit in the density of parvalbumin-immunoreactive neurons in the CA2 of patients with schizophrenia." (PMID 31632251, 2019). "Nine studies (comprising 136 schizophrenia patients and 138 healthy controls) measured parvalbumin neuron density in the pre-frontal cortex." (PMID 31529297, 2019). "There was a significant reduction in parvalbumin cell density in the pre-frontal cortex regions of patients with schizophrenia relative to healthy controls (Hedges’ g = − 0.27; z = − 2.17; p = 0.03; 95% confidence interval (CI): − 0.51 to − 0.03)." (PMID 31529297, 2019). "In addition, imaging studies in patients with schizophrenia show hyperactivity of the hippocampus, thought to be driven by stress-induced loss of inhibitory parvalbumin GABAergic interneurons, which may explain the relation between immune activation and mitochondrial function in this brain region." (PMID 29670128, 2018). "For example, post-mortem analysis of the PFC of schizophrenia patients has shown a 50% reduction in the expression of the NR2A subunit within inhibitory interneurons that express parvalbumin, a calcium binding protein." (PMID 30425662, 2018). "Parvalbumin+ cells have a reduction in mRNA and protein levels of parvalbumin itself despite unaltered neuronal density in patients with schizophrenia observed post-mortem." (PMID 30425662, 2018). "This prediction is consistent with recent data showing that the number of excitatory synapses onto parvalbumin-expressing inhibitory neurons is reduced in schizophrenia." (PMID 30067746, 2018). "In accordance with this, the antioxidant N-acetyl cysteine was reported to prevent the reduction of prefrontal parvalbumin interneuron activity as well as electrophysiological and behavioral deficits in the animal models of schizophrenia." (PMID 29515467, 2018). "In fact, schizophrenia has dysfunction of GABAergic cortical interneurons that express the calcium-binding protein parvalbumin, particularly in the prefrontal cortex." (PMID 30705645, 2018). "Inhibitory parvalbumin+ interneurons contribute to the cognitive deficits in schizophrenia and in unmedicated patients with the illness." (PMID 30425662, 2018). "For example, the level of Gad1 mRNA encoding GAD67 (glutamic acid decarboxylase-67) falls below detectable levels in approximately 50% of parvalbumin (PV)-positive prefrontal cortex (PFC) interneurons in schizophrenia." (PMID 29362511, 2018). "Parvalbumin+ cells have been extensively studied in schizophrenia and evidence of their dysfunction extends well beyond their contribution to the GBO." (PMID 30425662, 2018). "Findings from the Df16A± mouse model of schizophrenia demonstrate impaired social behavior, decreased number of parvalbumin-expressing interneurons in CA2, decreased activity of CA2 pyramidal neurons, and decreased synchrony between hippocampus and PFC." (PMID 30387713, 2018). "Parvalbumin-positive GABA neurons are selectively altered in schizophrenia patients and can account for abnormal circuit synchrony and cognitive deficits in this disorder." (PMID 28588483, 2017).
schizophrenia (continued). "It has been suggested that a functional deficit in NMDA-receptors (NMDARs) on parvalbumin (PV)-positive interneurons (PV-NMDARs) is central to the pathophysiology of schizophrenia." (PMID 27070406, 2016). "Rats exposed during embryonic day 17 to methylazoxymethanol acetate exhibit characteristics consistent with an animal model of schizophrenia, including decreased parvalbumin interneurons in the ventral hippocampus." (PMID 27432008, 2016). "Postmortem studies have demonstrated GABA deficits in a subclass of fast-spiking interneurons expressing Ca2+-binding protein parvalbumin in patients with schizophrenia." (PMID 28003912, 2016). "These behavioural deficits were accompanied by a decrease in parvalbumin-positive interneurons in the medial prefrontal cortex (a cellular endophenotype for schizophrenia) of DISC1 × neonatal immune challenge mutants." (PMID 27725886, 2016). "Other treatments early in life, such as antipsychotics or antioxidants, have also been shown to effectively protect parvalbumin interneurons and prevent other schizophrenia-like symptoms from emerging in developmental disruption models of schizophrenia." (PMID 27432008, 2016). "These animal studies strongly suggest a link between abnormalities in parvalbumin interneurons and schizophrenia." (PMID 27872809, 2016). "One of the common findings in both animal models and postmortem tissue from patients with schizophrenia is a reduction of mRNA or protein levels of the calcium-binding protein parvalbumin in cortical fast-spiking (FS) interneurons." (PMID 27725886, 2016). "Post-mortem studies of calretinin-, calbindin-, and parvalbumin-immunoreactive neurons in patients with schizophrenia, bipolar patients, and patients with major depressive disorder compared to control subjects." (PMID 26578879, 2015). "Consistent with deficits of gamma-band activity, parvalbumin-immunoreactive neuron density has been shown to be reduced in patients with schizophrenia and autism, as wells as in the brain of animal models of these diseases." (PMID 25803852, 2015). "Forthcoming investigations should also focus on the distribution and the densities of parvalbumin-immunoreactive neurons in the septal nuclei of patients with schizophrenia and patients with affective disorders compared with healthy control cases." (PMID 26578879, 2015). "Alterations in parvalbumin (PV)-positive cells in the brain are known to play a role in cognitive impairment in schizophrenia." (PMID 26107664, 2015). "As a positive control for the present collection of brains from subjects with schizophrenia, parvalbumin mRNA was measured by RT-PCR (G)." (PMID 25786133, 2015). "Meanwhile, the Notch4 locus has been identified as a candidate susceptibility gene for schizophrenia, and the mRNA level of Notch1 is differentially expressed in parvalbumin-immunoreactive neurons in subjects with schizophrenia." (PMID 26232790, 2015). "Increased oxidative stress and changes in antioxidant systems, such as decreased glutathione, in schizophrenia compromise the integrity of parvalbumin interneurons in the ventral hippocampus." (PMID 26578879, 2015). "It has been suggested that NMDA receptor hypofunction and alterations in the parvalbumin-positive interneurons are involved in schizophrenia in mice and in humans, but PPI was not measured in these studies." (PMID 24096375, 2013). "Our study using NMDAR hypofunction animal model revealed that redox dysregulation due to a decrease in PGC-1α abundance in cortical parvalbumin interneurons exacerbated schizophrenia-like phenotypes following social isolation stress." (PMID 24027504, 2013). "It should be noted that, in post-mortem brains ofpatients with schizophrenia, the number of parvalbumin+ interneurons and PNN+ cells is decreased in the prefrontal cortex." (PMID 24228616, 2013). "Parvalbumin immunoreactivity in the hippocampus is reduced in patients with schizophrenia (as shown in postmortem samples)." (PMID 23755033, 2013).